HTRA1 (HtrA serine peptidase 1)
Diseases named in the same sentence as HTRA1 in open-access papers (continued):
Sharing a sentence is not in itself a finding about the gene and the disease.
colorectal tumor (1 paper, 2020). "In the present study we evaluated the expression of the HTRA1-3 genes, encoding human HtrA serine proteases HtrA1, HtrA2, and HtrA3 isoforms (HtrA3L and HtrA3S), at both mRNA and protein levels, in colorectal tumor tissue and unchanged colorectal mucosa of the CRC patients." (PMID 32486357, 2020). "In colorectal tumor tissues, HtrA1 and HtrA3 were detected in both tumor cells and stromal compartment." (PMID 32486357, 2020). "Of the analyzed cases, 61 % of colorectal tumors had lower level of HtrA1 when compared to corresponding colorectal mucosa, whereas the HtrA2 protein level was lower in 71 % of the tumors." (PMID 32486357, 2020). "Our results showing a decrease in HtrA1 protein level in colorectal tumors are in agreement with results of several groups and our previous findings demonstrating a reduction of the protease content or even loss in other primary tumors." (PMID 32486357, 2020). "We found that the HTRA1 transcript level was significantly higher in the colorectal tumor tissue than in the unchanged colorectal mucosa, specifically in tumor tissue from patients with metastatic CRC, with metastases present in lymph nodes and distant organs (combined stages III and IV)." (PMID 32486357, 2020). "Moreover, a reduced level of HtrA1 in colorectal tumors was found to be correlated with worse patient survival." (PMID 32486357, 2020). "Their results revealed that the HtrA1 protein level was lower in colorectal tumors." (PMID 32486357, 2020). "Thus, the observed reduced HtrA1 protein level in colorectal tumors might promote cancer development and progression." (PMID 32486357, 2020).
diabetic retinopathy (1 paper, 2020). "High levels of hs-CRP are reported to be found in patients with diabetic retinopathy, AMD, and AMD high-risk variants of ARMS2/HTRA1 SNPs." (PMID 32503322, 2020).
disc degeneration (1 paper, 2025). "Refined clustering and classification distinguished the fibrocyte-like populations as subtypes in the NP cells - and immunocytes-clusters, expressing disc degeneration markers HTRA1 and ANGPTL4 and genes related to response to TGF-β." (PMID 39828732, 2025).
Doyne honeycomb retinal dystrophy (1 paper, 2018). Doyne honeycomb retinal dystrophy (DHRD) is a condition that affects the eyes and causes vision loss. "In addition, two novel targets of HTRA1 have been identified: EFEMP1, an extracellular matrix protein mutated in Doyne honeycomb retinal dystrophy, a genetic eye disease similar to AMD, and thrombospondin 1 (TSP1), an inhibitor of angiogenesis." (PMID 29730901, 2018).
endometriosis (1 paper, 2024). The growth of functional endometrial tissue in anatomic sites outside the uterine body. "NLRP3 inflammasome activation through IncRNA NEAT/miR-141-3p/HTRA1 pathway contributes to endometriosis." (PMID 39769450, 2024). "have shown that NLRP3 inflammasome activation through IncRNA NEAT/miR-141-3p/HTRA1 pathway leads to endometriosis." (PMID 39769450, 2024).
esophageal tumor (1 paper, 2012). "The more highly undifferentiated esophageal tumor cells expressed lower HtrA1 mRNA and protein expression levels (p < 0.05)." (PMID 22935172, 2012).
Familial adenomatous polyposis (1 paper, 2016). Familial adenomatous polyposis (FAP) is characterized by the development of hundreds to thousands of adenomas in the rectum and colon during the second decade of life. "In addition, the Htra1 promoter is methylated and repressed in a proportion of benign polyps that develop in the ApcMin+ mouse model of human familial adenomatous polyposis." (PMID 27388476, 2016).
glioblastoma (1 paper, 2024). The most malignant astrocytic tumor (WHO grade IV). "We also investigated the function of HTRA1 in glioblastoma (GBM) cells in vitro and in vivo, and found that HTRA1 promoted tumor progression by enhancing proliferation, invasion, and migration." (PMID 38334007, 2024).
glomerulonephritis (1 paper, 2025). A renal disorder characterized by damage in the glomeruli. "Several podocyte antigens, such as PLA2R1, THSD7A, NELL1, HTRA1, and nephrin, are the primary targets of deleterious autoantibodies in glomerulonephritis patients." (PMID 40072092, 2025).
Impaired glucose tolerance (1 paper, 2024). An abnormal resistance to glucose, i.e., a reduction in the ability to maintain glucose levels in the blood stream within normal limits following oral or intravenous administration of glucose. "We further identified the proteins CBPM and serine protease HTRA1, which we have previously shown to be strongly discriminative for impaired glucose tolerance and to be associated with body fat distribution and inflammation." (PMID 37889320, 2024).
invasive carcinoma (1 paper, 2012). A carcinoma that is not confined to the epithelium, and has spread to the surrounding stroma. "In marked contrast, HtrA1 expression was greatly reduced or lost entirely in DCIS and invasive carcinomas (CA panels)." (PMID 22761798, 2012).
lymph node metastasis (1 paper, 2012). "Patients with positive lymph node metastasis had significantly lower HtrA1 mRNA and protein expression levels than did patients with lymph node-negative disease (p < 0.05)." (PMID 22935172, 2012). "Patients with positive lymph node metastasis had significantly lower HtrA1 protein expression levels than did patients with lymph node-negative disease (p < 0.05)." (PMID 22935172, 2012). "Patients with positive lymph node metastasis had significantly lower HtrA1 mRNA and protein expression levels versus patients with lymph node-negative disease (p < 0.05)." (PMID 22935172, 2012). "Patients with positive lymph node metastasis had significantly lower HtrA1 mRNA expression levels than did patients with negative lymph node metastasis (p < 0.05)." (PMID 22935172, 2012).
macular dystrophies (1 paper, 2015). "Initial studies focused on HTRA1 because its overexpression might destroy the integrity of Bruch's membrane and lead to neovascularization, whereas ARMS2 protein was recently found to bind several matrix proteins that had been demonstrated to cause AMD or play roles in macular dystrophies." (PMID 25883802, 2015).
neuroblastoma (1 paper, 2016). Neuroblastoma (NB) is the most common solid, extracranial childhood tumor. "We also focused on the serine-protease HTRA1 since its low expression levels strongly correlate with neuroblastoma progression." (PMID 27009842, 2016). "A recent study has reported that the expression of HtrA1 protein is lower in advanced neuroblastomas." (PMID 27009842, 2016).
ovarian disorder (1 paper, 2024). A disease involving the ovary. "The dysregulation of HtrA1 may disrupt ovarian tissue homeostasis, potentially contributing to ovarian disorders." (PMID 38793064, 2024). "Based on the protein profiling data, the expression of HTRA1 was significantly greater in the enhanced exosomes than in the naïve exosomes, suggesting the potential increase in the therapeutic efficacy of enhanced exosomes for treating ovarian disorders." (PMID 38793064, 2024). "Our findings revealed distinct cargo compositions in enhanced exosomes, featuring upregulated proteins such as EFEMP1, HtrA1, PAM, and SDF4, suggesting their potential for treating ovarian disorders." (PMID 38793064, 2024).
ovarian dysfunction (1 paper, 2024). The inability of the ovaries to function. "The overexpression of EFEMP1, HtrA1, PAM, and SDF4 in enhanced exosomes compared to naïve exosomes underscores their potential therapeutic relevance in treating ovarian dysfunction." (PMID 38793064, 2024).
periodontal diseases (1 paper, 2014). "In addition, we observed the presence of HtrA1 in normal and pathological epithelium, with an increased expression, particularly in its superficial layer, associated with increasingly severe forms of periodontal disease." (PMID 24979214, 2014). "Our findings highlight a correlation of plasma cell HtrA1 expression with the occurrence of periodontal diseases and a possible contribution of epithelial HtrA1 to the control of periodontal infection." (PMID 24979214, 2014). "Therefore, the present study supports the hypothesis that HtrA1 protein expressed in plasma cells can indirectly take part in periodontal lesions, contributing to pathological tissue remodelling in periodontal diseases." (PMID 24979214, 2014).
pleural mesothelioma (1 paper, 2015). A neoplasm that arises from the mesothelial cells of the pleura. "A longer OS was also measured in patients with pleural mesothelioma showing higher HtrA1 levels." (PMID 26035313, 2015).
pregnancy disorder (1 paper, 2014). A disorder that is related to pregnancy. "Since HtrA1, HtrA3 and HtrA4 share identical domain organization, our results establish important foundations for developing potential therapeutics to target these HtrA proteins specifically for the treatment of a number of diseases, including cancer and pregnancy disorders." (PMID 25248123, 2014).
rectal cancer (1 paper, 2021). A primary or metastatic malignant neoplasm that affects the rectum. "Whether SPINK4 can downregulate HTRA1 to activate the PI3K/AKT pathway involved in rectal cancer metastasis needs further verification." (PMID 34202399, 2021). "Therefore, whether SPINK4 can induce chemoresistance and metastasis indirectly through serine protease HTRA1 inhibition in rectal cancer deserves further verification." (PMID 34202399, 2021).
retinal vein occlusion (1 paper, 2024). An occlusion of the retinal vein. "We measured the protein concentrations of HTRA1, the three isoforms of TGF-β, and VEGF-A (hereinafter called VEGF) in human vitreous humor from patients with chorioretinal vascular diseases, including AMD, DR, and retinal vein occlusion (RVO)." (PMID 39274287, 2024).
sarcopenia (1 paper, 2021). Progressive decline in muscle mass due to aging which results in decreased functional capacity of muscles. "Apelin and HtrA1 were inversely associated with the presence of sarcopenia with an OR of 0.543 (95%CI: 0.397–0.743) and 0.003 (95%CI: 0.001–0.890) after full adjustment." (PMID 33743591, 2021). "In the present study, we found that HtrA1 and apelin were significantly associated with sarcopenia and provide a potential approach in molecular diagnosis of in older adult population." (PMID 33743591, 2021). "The cutoff point of HtrA1 was associated with the presence of sarcopenia with an OR of 0.254 (95%CI: 0.083–0.778) in men." (PMID 33743591, 2021). "In our study, we found that HtrA1 was associated with the presence of sarcopenia, particularly in men." (PMID 33743591, 2021). "HtrA1 was associated with decreased presence of sarcopenia with an OR of 0.003 (95%CI: 0.001–0.890) after full adjustment." (PMID 33743591, 2021). "We found that HtrA1 was associated with decreased presence of sarcopenia in older men and apelin is significantly associated with reduced occurrence of sarcopenia, in women." (PMID 33743591, 2021). "A previous study have reported several biomarkers such as high temperature requirement serine protease A1 (HtrA1), procollagen III N-terminal peptide (P3NP), apelin, and heat shock protein 70 (Hsp72) are possibly involved in different components of sarcopenia." (PMID 33743591, 2021).
schizophrenia (1 paper, 2022). A major psychotic disorder characterized by abnormalities in the perception or expression of reality. "Finally, dysregulation of glutamatergic and serotoninergic genes, such as Grina, Htra1, and Tph2, has been reported in several NDs, and Esyt1 is increased in the brain from schizophrenia patients." (PMID 35268026, 2022).
Thiel-Behnke corneal dystrophy (1 paper, 2019). Thiel-Behnke corneal dystrophy (TBCD) is a rare form of superficial corneal dystrophy characterized by sub-epithelial honeycomb-shaped corneal opacities in the superficial cornea, and progressive visual impairment. "One group was resistant to HtrA1 proteolysis and contained WT and the R555W and R555Q mutations associated with the nonamyloidogenic phenotypes GCD and Thiel-Behnke corneal dystrophy (TBCD)." (PMID 31197037, 2019).
thymoma (1 paper, 2020). A neoplasm arising from the epithelial cells of the thymus. "Based on the same PRM validation sample batch we also examined TSCC/thymoma marker candidates such as CNOT2/9, SHMT1, VCAN, HTRA1, and TIMP1 in parallel with CK19 in the PRM analysis (for raw fragment abundances of all PRM samples)." (PMID 31967407, 2020). "Further comparison of type B3 and TSCC proteome revealed a number of differential proteins with similar expression patterns: CNOT2/9 and SHMT1 were found with high abundance in type B3 thymoma, while the abundance of HTRA1, TIMP1, and VCAN was higher in TSCC than in type B3 thymoma." (PMID 31967407, 2020).
ulcerative colitis (1 paper, 2021). An inflammatory bowel disease involving the mucosal surface of the large intestine and rectum. "In an analysis of tissue specimens from Caucasian Italian subjects, HtrA1 expression was negatively correlated with ulcerative colitis duration and functioned as a biomarker to identify patients with ulcerative colitis of > 10 years duration (UCL) who were at high risk of developing CRC." (PMID 34563186, 2021).
infection (77 papers, 2004 to 2026). The state of being infected such as from the introduction of a foreign agent such as serum, vaccine, antigenic substance or organism. "By GD18, infection-induced changes in placental bed IL-18, Htra1, and uNK cells were equivalent between control and infected groups." (PMID 36042379, 2022). "Collectively, infection-induced changes in placental bed IL-18 and Htra1 involved cells that participate in spiral artery remodeling (i.e., uNK cells and endovascular invasive trophoblasts)." (PMID 36042379, 2022). "Taken together, these data suggest that both HtrA1 and Ply may be involved in the infection process employed by SP, and their effects are likely neutralized in the presence of SS." (PMID 38903015, 2024).
tumor (63 papers, 2008 to 2026). "The loss of expression of HTRA1 leads to an increase in tumor invasiveness, enhanced metastatic ability and chemotherapeutic resistance." (PMID 38686366, 2024). "In order to better understand why HTRA1 is often implicated as a tumor suppressor, we examined its effect on cellular proliferation abilities, and as an indicator of the tumorigenic traits of cells." (PMID 29269789, 2017). "Downregulation of the HTRA1 gene in tumour cells has been linked with epigenetic mechanisms and the HTRA1 promoter was identified as a target of the histone deacetylase HDAC1." (PMID 27388476, 2016). "Previous studies have suggested that HTRA1 is a tumor suppressor: it is down-regulated in various cancers, and its down-regulation is associated with tumor proliferation, chemotherapy resistance and a metastatic phenotype." (PMID 27166271, 2016). "Our findings may also have implications in the clinic, as the methylation state of the HtrA1 promoter may act as a convenient biomarker for tumour cells or cells at risk of transformation." (PMID 27388476, 2016). "Since all mutations are predicted to affect HTRA1 protein stability, we suggest that the observed variants may act as loss-of-function mutations that enhance invasion or metastasis of tumor cells." (PMID 27009842, 2016). "In addition to its potential role as a tumor suppressor, HtrA1 also has been implicated in chemotherapeutic responsiveness." (PMID 22761798, 2012). "In addition, previous research has reported that HtrA1 protein expression is associated with tumor migration and metastasis." (PMID 22935172, 2012). "This means that the reduced HtrA1 expression may be closely associated to tumor development." (PMID 29409460, 2018). "Moreover, the methylation state of the HTRA1 promoter may be explored as a potential biomarker for tumour cells or cells at risk of transformation." (PMID 27388476, 2016). "Downregulation of HTRA1 causes a number of phenotypes that are hallmarks of cancer cells suggesting that the methylation state of the HtrA1 promoter may be used as a biomarker for tumour cells or cells at risk of transformation." (PMID 27388476, 2016). "Thus, as a consequence of HTRA1 loss, resistance to anoikis (detachment-induced apoptosis) may contribute to tumor cell dissemination and invasion in metastatic cancer." (PMID 23580433, 2013). "The results showed that DCBLD2 and HTRA1 were highly expressed in tumor tissues, and DCBLD2 was mainly expressed in fibroblasts and myofibroblasts, HTRA1 was mainly upregulated in endothelial cells and fibroblasts." (PMID 39790460, 2025). "A reduced expression of HTRA1 was detected in several malignant tumors including ovarian carcinoma, melanoma and endometrial carcinoma, and it is considered as a tumor suppressor gene." (PMID 38740771, 2024). "HTRA1 was shown to suppress the proliferation of tumor cells by inhibiting Wnt/β‐catenin through complexing with β‐catenin." (PMID 38334007, 2024). "High‐temperature requirement‐A1 serine protease (HTRA1), also named as serine protease 11 (PRSS11), is one of the proteins participating in tumor invasion and migration." (PMID 38334007, 2024). "In this study, we firstly verified that the relative mRNA expressions of HTRA1 in tumor tissues of PDAC patients was higher than that in paracancerous tissues through the existing database." (PMID 38287020, 2024). "Although HTRA1 has not been fully studied in the kidney, previous studies on malignant tumors suggest that HTRA1 has tumor suppressive effects." (PMID 38686366, 2024). "Consistently, western blot analyses showed that HTRA1 expression was higher in fresh CRC tissues than in matched non-tumor tissues." (PMID 38740771, 2024). "Recently, a meta-analysis was conducted to assess the potential role of HtrA1 as a tumor marker and/or prognostic factor in several tumors." (PMID 38372785, 2024). "To study the effect of HTRA1 on in vivo tumor growth, we stably knocked down HTRA1 in LN229 and GBM#P3 cells expressing luciferase." (PMID 38334007, 2024).